HMGB1 (high mobility group box 1)
Diseases named in the same sentence as HMGB1 in open-access papers (continued):
Sharing a sentence is not in itself a finding about the gene and the disease.
tumor (continued). "Also, dying tumor cells release a number of nuclear and cytoplasmic proteins like high mobility group box 1 (HMGB1) and annexin A1 (ANXA1)." (PMID 36003765, 2022). "The ‘Pathological Stage Plot’ module of GEPIA2 was used to examine whether HMGB1 expression may differ in different pathological stages of tumours." (PMID 35765707, 2022). "Additionally, HMGB1 can be produced from a variety of tumor cells in response to chemo or radiation therapy, and as a result, it plays a role in the regulation of cancer cells’ chemoresistance and sensitivity." (PMID 36428714, 2022). "HMGB1 might reflect tumor necrosis pretherapeutically and it potentially qualifies as a follow-up marker." (PMID 34671818, 2022). "Therefore, it is necessary to clarify the effects of DAMPs such as HMGB1 on tumor metabolism and their dual roles in promoting or inhibiting cancer progression." (PMID 36050306, 2022). "In addition, high mobility group protein B1(HMGB1) released by dead tumor cells can bind to Toll-like receptors-4 (TLR4) receptors on the surface of DCs and promote antigen presentation while promoting the production of proinflammatory factors." (PMID 36355531, 2022). "HMGB1 production positively correlates with tumor antigen-specific T cell response and thus could serve as a biomarker for patient prognosis." (PMID 35432318, 2022). "HMGB1 is a potential marker for the prognosis of various tumours." (PMID 35379200, 2022). "As for the tumor microenvironment, the rapid growth of cells and inadequate supply of oxygen and blood nutrients will induce the release of some proinflammatory mediators, such as IL-1 and HMGB1." (PMID 35484993, 2022). "ECT induces ICD through the liberation of ATP, HMGB1, and calreticulin, which in turn might increase the tumor infiltration of several immune cells, including CD8+ T cells and NK cells." (PMID 35740542, 2022). "Tumor irradiation induces the danger signal, including a CRT translocation to the cell surface, and releases the damage-associated molecule patterns (DAMPs), such as HMGB-1, which promotes tumor antigen recognition by dendritic cells and T cell activation." (PMID 35565217, 2022). "An increase in HMGB1 in the tumor microenvironment leads to an increase in HMGB1–RAGE interactions." (PMID 36359780, 2022). "Here, we conducted a pan‐cancer analysis of HMGB1 in malignant tumours." (PMID 35765707, 2022). "HMGB1 is a nuclear protein that initiates inflammation through Toll-like receptors or advanced glycation products and induces the invasion and migration of malignant tumor cells." (PMID 35872698, 2022). "Furthermore, we also measured CRT and HMGB1 expression in the tumor section of the mice sacrificed on day 20 to further confirm the ICD." (PMID 37693071, 2022). "In humans, HMGB proteins also play a role in DNA repair, and increased expression of HMGB1, one type of HMGB protein, is associated with tumor progression or metastasis, suggesting that HMGB proteins are closely related to maintaining ordered cell proliferation." (PMID 35905103, 2022). "HMGB1 can secrete or release cells as injury-related molecules, and bind with its receptors to participate in inflammation, cell differentiation, cell migration, angiogenesis, tumor metastasis, drug resistance, and other processes." (PMID 35886594, 2022). "In addition, HMGB1 released from IRE-treated tumor cells have been shown to reprogram TAMs from immune-suppressive (M2) to immune-promoting (M1) phenotypes, thereby increasing the M1/M2 ratio in the TME and the periphery." (PMID 35740542, 2022). "The release of CALR, ATP, and HMGB1 molecules by dying cancer cells occurs within hours, a slow increase in T cells begins after 100 h, which peaks at 200 h, and the tumor cells are eliminated in about 220 h when a rapid increase in cytotoxic T lymphocyte cell population begins." (PMID 37420422, 2022).
tumor (continued). "Likewise, CM from co-culturing B cells with GL-treated HMGB1-overexpressing tumor cells significantly reduced HUVEC transmigration via transwell assay (77.42% and 52.03% reduction in EC18H/B and K510H/B, respectively) and live-cell imaging." (PMID 34617194, 2022). "Furthermore, release of high-mobility group box 1 (HMGB1) induced by the inhibition of autophagy in hepatocytes leads to tumor development." (PMID 34657993, 2022). "Notably, ATP and HMGB1 were secreted in some tumor models even at sublethal doses of radiation, while CRT surface translocation, classically a cardinal sign of immunogenic cell death, occurred in all tumor models at sublethal doses of radiation." (PMID 36497086, 2022). "Recent advances have demonstrated that some chemotherapeutics including PTX could act as immunogenic cell death inducers by arousing calreticulin exposure on tumor cell surface and the release of high mobility group box 1 from tumor cells." (PMID 36303207, 2022). "In all three patients with decreasing HMGB1, follow-up revealed tumor recurrence (p = 0.001)." (PMID 34671818, 2022). "Hypoxia is one of the pivotal factors that induce elevated HMGB1 levels in tumor tissues." (PMID 35637945, 2022). "The in vivo results using CM from co-culture systems showed that the role in tumor growth suppression of GL/anti-HMGB1 mAb might be dictated by the presence of HMGB1, irrespective of B cells." (PMID 34617194, 2022). "The HMGB1 serves as a double‐edged sword for patients with different tumours." (PMID 35765707, 2022). "HMGB1 enhances tumor invasion and metastasis and accelerates tumor growth." (PMID 35795049, 2022). "The levels of HMGB1 are commonly increased in numerous cancer types compared with their parental normal tissues, proposing HMGB1 expression generally acts to promote tumor progression." (PMID 36047643, 2022). "To investigate whether the presence of HMGB1 within the tumor nest could have an impact on predicting patients’ survival, we stratified patient samples into low or high variance groups." (PMID 34617194, 2022). "HMGB1 is released by dying tumor cells after nuclear and cytoplasmic membrane permeabilization." (PMID 36429101, 2022). "HMGB1 is released extracellularly from dead tumor cells at the late stage of ICD." (PMID 36230638, 2022). "Current evidence supports a pro-tumorigenic role of HMGB1 during tumor development." (PMID 36032129, 2022). "Targeting HMGB1 is an effective strategy to improve the tumor inflammatory microenvironment." (PMID 36506511, 2022). "In addition, liver IRI-induced NETs also contain HMGB1, and NET-derived HMGB1 enhances tumor invasiveness by inducing the epithelial to mesenchymal transition (EMT) program." (PMID 36211432, 2022). "The molecular reason for these differences in association with tumor stage of HMGB2 vs. HMGB1/3 is not yet understood." (PMID 35923467, 2022). "Notably, HMGB1 was found to promote tumor proliferation and migration via activation of the RAGE receptor, Wnt/β-Catenin and MAPK pathways." (PMID 36142453, 2022). "• N2 GANs suppress T cell immunity and induce genetic instability, tumor cell proliferation, angiogenesis, and metastasis• NETs induce the IL-8 expression, which is correlated with tumor burden and prognosis through a HMGB1- and RAGE/ERK/NF-kB axis-dependent manner." (PMID 35711434, 2022). "However, the dual function of pro- and anti-tumor makes HMGB1 in cancer progression requires more profound understanding." (PMID 35637945, 2022). "Three lines of evidence promote the search for a new type of anti-cancer agent possessing a higher anti-inflammatory activity, targeting high-mobility group box 1 (HMGB1)–receptor for advanced glycation end-products (RAGE) signaling pathway in the tumor microenvironment (TME)." (PMID 35408786, 2022). "Based on our work, ESCC tumor-derived HMGB1 assumes a strong influence in B cells." (PMID 34617194, 2022).
tumor (continued). "However, in GB1388 specimen with lower levels of autophagy (lower expression of LC3B, STX17 and higher expression of SQSTM1), HMGB1 accumulated in the nuclei and cytoplasm of tumor cells." (PMID 35193644, 2022). "Furthermore, another study showed that HMGB1 silences a tumor growth and metastasis repressor semaphorin SEMA3A via directly binding to its genomic locus, promoting heterochromatin formation and decreased occupancy of acetylated histones." (PMID 35679251, 2022). "In addition, MVA-TAA-4-IBBL induced strong ICD with HMGB1 exposure and generated tumor-specific immune memory that eliminated local and distant tumor relapse." (PMID 36755812, 2022). "On the one hand, pyroptosis, a lytic and proinflammatory type of regulated cell death, is characterized by cell swelling, lysis, and the release of numerous proinflammatory factors, including IL-18, ATP, IL-1β, and HMGB1, which can promote tumor growth and progression." (PMID 35784306, 2022). "The regulation of HMGB1 function might affect and change the tumor biology and aid in the prevention and treatment of cancer in multicancer cases." (PMID 36230798, 2022). "Additionally, HMGB1 function is also remarkably related to the tumor immune microenvironment and immune infiltration, especially regarding the high purity of stromal and immune cells in the tumor microenvironment (TME)." (PMID 36230798, 2022). "Therefore, this study aimed to investigate HMGB1 extracellular release from tumor cells during BPA-based BNCT." (PMID 35336794, 2022). "For instance, hypoxia induces the expression of the high-mobility group B1 (HMGB1) in the tumor cell-released autophagosomes (TRAPs), which in turn induce IL-10 production in B cells, with a consequent suppression of T cell function and thus protection for tumors against immune response." (PMID 35565420, 2022). "If immunogenic tumor cell death were induced by chemotherapy or radiation therapy, the effect of HMGB1-knockout could be more apparent." (PMID 35150340, 2022). "HMGB1 is actively involved in tumor growth, cell proliferation, metastasis, and invasion." (PMID 36428714, 2022). "However, a new finding in tumor biology reveals that sulfonyl HMGB1 exerted anti-inflammatory effects via the RAGE signaling pathway, which can recruit immune-competent cells and inhibit cytotoxic cells." (PMID 35837232, 2022). "The expression of HMGB1 is upregulated in various tumor tissues compared to normal tissues." (PMID 36428714, 2022). "Promoted infiltration of immune cells in HMGB1-knockout tumor tissues might be a result of mitigation of local immunosuppression by Treg and MDSCs." (PMID 35150340, 2022). "Moreover, HMGB1 mediates tumor immune escape by promoting the proliferation and differentiation of myeloid-derived suppressor cells, inducing regulatory T cells or B cells." (PMID 34617194, 2022). "Since tumor-derived HMGB-1 may inhibit anti-tumor T cell responses through the ligation of TIM-3 on T cells and the up-regulation of HLA-G on tumor cells, an inhibitor of HMGB-1 may be tested in combination with anti-HLA-G antibodies." (PMID 35328349, 2022). "However, the tumour weight and volume of the miR-495-3p and HMGB1 lentivirus group were between those of the former two groups." (PMID 35354479, 2022). "This striking association led us to set up models to test whether cancer-derived HMGB1 could shape tumor microenvironment via modulation on B cells." (PMID 34617194, 2022). "In this retrospective study of RCC patients, using a population‐based cancer registry and inpatient immunohistochemistry data in Japan, we sought to examine whether there are occupational disparities in tumor grade and cytosolic HMGB1 expression." (PMID 35712799, 2022). "However, the role of HMGB1 in the anti-tumor immunity is unclear since inflammation in the tumor microenvironment also contributes to tumor promotion and progression." (PMID 35150340, 2022).
tumor (continued). "Tumor cell-released autophagosomes are sufficient to suppress the antitumor immune response in the mouse by inducing IL-10-producing B cells through high-mobility group B1 (HMGB1)." (PMID 36233088, 2022). "Hence, extracellular HMGB1 has a powerful ability to coordinate different immune responses in the tumor microenvironment." (PMID 35637945, 2022). "Release of HMGB1 from dying tumor cells may be required to empower DCs to process and present tumor antigens." (PMID 35637945, 2022). "Extracellular HMGB1, released from the tumor cells under hypoxia, mediates communication between cells in the tumor microenvironment through binding several receptors, especially RAGE and TLR4, which contribute to tumor growth via sustenance of long-term inflammation." (PMID 36012593, 2022). "Thus, extracellular HMGB1 secreted by GB cells under TMZ treatment have little effect on tumor cells." (PMID 35193644, 2022). "HMGB1 can contribute to tumorigenesis, as HMGB1 produced by tumor cells may exacerbate inflammation-related immunosuppression." (PMID 35493517, 2022). "The results showed that inhibiting the expression of the ICD-related genes CDK12/13 could release HMGB1 and translocate calreticulin, and promote T cell dependent tumor inhibition." (PMID 36437951, 2022). "Several studies have assessed the role of HMGB1 in anti-tumor immunity." (PMID 35150340, 2022). "However, evidence on the relationship between HMGB1 and various tumor types in multicancer cases based on big clinical data is still lacking." (PMID 36230798, 2022). "Hence, future studies are expected to explore biological pathways of higher tumor grades from occupational stress in combination with lifestyle‐related risks to HMGB1 expression in RCC." (PMID 35712799, 2022). "Next, the expression of HMGB1 in tumour tissues and normal control tissues was compared." (PMID 35765707, 2022). "Current evidence suggests that extracellular HMGB1 release may act systemically as well as locally in the tumor microenvironment to promote tumor cell survival and inflammatory reactions in a paracrine manner." (PMID 35336794, 2022). "Further studies using immunocompetent and immunodeficient mice injected with syngeneic tumor cell lines will therefore be required to assess whether the in vitro anticancer activities of HMGB1 might be modulated in vivo by the immune system." (PMID 35887213, 2022). "Therefore, the increase in plasma level in the tumor-bearing BNCT group is due to the extracellular HMGB1 release during cell death." (PMID 35336794, 2022). "Enzalutamide upregulates high mobility group protein B1 (HMGB1) in the tumor cell cytoplasm." (PMID 35938167, 2022). "In addition, ordinary B cells in tumor tissues can convert into Breg cells, which depends on exosomal HMGB1 released from HCC cells." (PMID 35126514, 2022). "Additionally, photothermal therapy and the CDT-mediated ICD improve anti-tumor immunity by exposing HMGB1, CRT, and ATP." (PMID 36248807, 2022). "The results showed that the average sprout length in HUVECs treated with CM from co-culturing B cells with HMGB1-overexpressing tumor cells at 72 h was significantly longer (3.716 ± 5.062 μm/spheroid) than in those treated with control medium (1.692 ± 2.535 μm/spheroid)." (PMID 34617194, 2022). "Additionally, high-mobility group box 1 (HMGB1) proteins derived from dead tumor cells trigger toll-like receptor 4 (TLR4) on DCs to produce type I IFNs through myeloid differentiation factor 88 (MyD88) signaling." (PMID 35292881, 2022). "This may suggest that B cells are attracted toward HMGB1-expressing tumor front and we consequently focused on the chemotactic capacity of the B cells in response to HMGB1." (PMID 34617194, 2022). "Since the immune-regulatory functions of soluble factors are increasingly recognized in cancers, we hypothesized that tumor-derived HMGB1 can be pivotal for influencing B-cell polarization during development of ESCC." (PMID 34617194, 2022).
tumor (continued). "Furthermore, in this patient cohort, elevated serum HMGB1 was associated with antigen-specific T cell responses and the degree of HMGB1 expression in the tumor microenvironment (TME) was correlated with improved patient survival." (PMID 36497086, 2022). "Surprisingly, a decrease in the number of tumor cells could only be observed for the HeLa cell line when treated with 200 nM of either HMGB1-fl or HMGB1-ΔC." (PMID 35887213, 2022). "Moreover, both HMGB1 release and ATP secretion from the tumor cells treated with OPCPN@NTKPEG (+) exhibited over 2 times as many as those from the groups of OXA and OPCPN@NTKPEG." (PMID 35910806, 2022). "Furthermore, changes in the distribution of HMGB1 were observed when 9464D tumor bearing mice were administered CPM, with a decrease in strong nuclear staining compared to untreated tumors." (PMID 36097618, 2022). "Indeed, we initially observed that serum levels of HMGB1 in tumor-bearing mice, as well as that in supernatants of LLCs culture, were significantly increased." (PMID 36542153, 2022). "This suggests that HMGB1, and more specifically HMGB1-ΔC, preferentially targets tumor cells." (PMID 35887213, 2022). "As expected, HMGB1 was detected in the intratumoral locations of tumor samples." (PMID 34617194, 2022). "It enables CD8+ T cell recruitment to the tumor microenvironment, whereas HMGB1-stimulated autophagy may induce tumor resistance to chemotherapy." (PMID 35093187, 2022). "However, HMGB1 is also thought to have antitumor properties, and interestingly, it inhibits glycolysis in tumor cells, leading to metabolic cell death." (PMID 36050306, 2022). "Moreover, the levels of the immunogenic cell death markers, HMGB1 and calreticulin, were also remarkably upregulated in LP-treated apoptotic tumor cells compared with some other TLR agonists in vitro." (PMID 35764365, 2022). "HMGB1 acts as a key regulator in the crosstalk between GB cells and tumor-suppressive M1-like TAMs in GB microenvironment and may be considered as an adjuvant for the chemotherapeutic agent TMZ." (PMID 35193644, 2022). "Our study suggests that NOL7 might interact with HMGB1, thus functioning as a key mediator related to prognosis and the status of tumor immunity in cancers." (PMID 36077008, 2022). "Similarly, anthracyclines and oxaliplatin can induce tumor cell death via the release of HMGB1, which is recognized by TLR4 expressed on DCs and subsequently activates MyD88, resulting in type I IFN production." (PMID 35292881, 2022). "Based on the results of in vitro assays, extracellular HMGB1 also promoted local tumor growth and tumor metastasis in an in vivo assay, while treatment with rTM attenuated these effects, indicating the potential of rTM as a new therapeutic role for GC targeting extracellular HMGB1." (PMID 35328684, 2022). "The negative correlations were detected between HMGB1 expression and the immune infiltration of cancer‐associated fibroblasts in the TCGA tumours of HNSC_HPV+ based on all or most algorithms." (PMID 35765707, 2022). "For instance, in orthotopic mouse glioma models, NDV immunotherapy has been shown to increase calreticulin translocation to the cell surface and extracellular accumulation of high mobility group box 1 and a tumor-specific immune response and long-term tumor regulation." (PMID 35910836, 2022). "ICD-induced tumor cells release damage-associated molecular patterns (DAMPs) as danger signals, including calreticulin (CALR), high mobility group protein 1 (HMGB1), heat shock proteins (HSPs), and adenosine-5’-triphosphate (ATP), to activate the immune system and enhance antitumor immune responses." (PMID 36189310, 2022). "Moreover, in macrophages, AGER also mediates the inflammation in macrophages induced by high-mobility group box 1 (HMGB1), a damage-associated molecular pattern molecule released by ferroptotic tumor cells." (PMID 35372083, 2022).